REN (renin)
Diseases named in the same sentence as REN in open-access papers (continued):
Sharing a sentence is not in itself a finding about the gene and the disease.
Hypertension (continued). "Hypertension is pathologically related to hyperactivity of the renin-angiotensin system (RAS), and animal studies show the involvement of VDR activation in downregulating RAS." (PMID 35147511, 2022). "Several factors are highly involved in the emergence of uremic cardiomyopathy, including hypertension, anemia, renin-angiotensin system overactivation, microinflammation, CKD mineral-bone disorder (CKD-MBD), and uremic toxins." (PMID 35903671, 2022). "Hypertension is regulated mainly by the autonomic nervous system, the renin–angiotensin system, and nitric oxide (NO)." (PMID 35205232, 2022). "Based on the observation that human placenta chemically induces systemic hypertension, an old rodent model has been applied to simulate gestational hypertension by manipulating the renin-angiotensin system." (PMID 36068569, 2022). "In humans with weight excess and hypertension, renin inhibitors (e.g., aliskiren) and ACEi (e.g., ramipril), improve renal and systemic hemodynamics and reduce arterial pressure." (PMID 36519165, 2022). "Both studies attributed elevated blood pressure or hypertension to enhanced production of renin and angiotensin II due to the effect of FF homozygotes." (PMID 35282461, 2022). "Overactivity of the renin-angiotensin system is another reason for hypertension in dialysis patients." (PMID 36000139, 2022). "Due to therapy resistant hypertension and hypokalaemia, screening for secondary hypertension was performed and displayed high s-cortisol (3,370 nmol/L) and normal aldosterone/renin ratio [27 mIU/L (normal 4–65 mIU/L)]." (PMID 36111117, 2022). "Aldosterone is one of the main effectors of the renin-angiotensin-aldosterone system (RAAS) along with having roles in hypertension, and cardiovascular and renal diseases." (PMID 35453295, 2022). "Renal renin AV-Δ at baseline and during an HC should be investigated in human hypertension to assess the approach’s suitability for patient selection and procedural guidance." (PMID 33136224, 2022). "Angiotensin II (Ang II), an important member of renin-angiotensin-aldosterone system, contributes to many cardiovascular diseases, such as cardiomyopathy and heart failure, hypertension, atherosclerosis and arrhythmia." (PMID 36613786, 2022). "According to the KEGG analysis, the Toll-like receptor, MAPK, PI3K-Akt, TNF, NOD-like, NF-κB, and renin-angiotensin signaling pathways are major targets of GJD in the treatment of hypertension." (PMID 36046450, 2022). "REN mRNA overexpression and the downregulation of two miRNAs (hsa-miR-181 and hsa-miR-663) which influence REN mRNA levels indicate the involvement of renin in the etiology of hypertension." (PMID 35369298, 2022). "More importantly, however, our data support a more prominent role of the intratubular renin/ACE/Ang II/AT1a/NHE3 axis in the proximal tubules in the development of 2K1C hypertension." (PMID 36555438, 2022). "Most patients with low-renin hypertension have sodium-volume-dependent hypertension, suggesting that high sodium uptake leads to fluid retention and decreased renin activity to compensate." (PMID 35448080, 2022). "Vitamin D is an inhibitor of renin biosynthesis and a modulator of RAAS activity; therefore, VDR dysregulation will increase renin and angiotensin II levels, which in turn leads to hypertension and cardiac hypertrophy." (PMID 36142634, 2022). "A major trigger of hypertension and hypertension-dependent disease is the overactivation of the renin-angiotensin-aldosterone system (RAAS)." (PMID 36552716, 2022). "Activation of the renin-angiotensin-aldosterone system (RAAS) plays a critical role in the development of hypertension." (PMID 35360022, 2022). "BAC targets ACE/ACE2 to enhance endothelium-dependent vasorelaxation and reduce vascular inflammation to attenuate hypertension as a potential modulator of the renin–angiotensin system." (PMID 35359841, 2022).
Hypertension (continued). "Elevated corticosterone and deoxycorticosterone (DOC) levels lead to increased mineralocorticoid activity and subsequent sodium retention, volume expansion, and hypertension with suppressed renin and aldosterone." (PMID 36110215, 2022). "The classic and probably the most studied pathophysiological pathway in hypertension, is the renin-angiotensin-aldosterone system (RAAS)." (PMID 35627493, 2022). "The recent introduction of endovascular catchers to lower moderate/resistant hypertension has yielded promising results due to its ability to dampen the renin-angiotensin-aldosterone axis." (PMID 35094013, 2022). "In hemodialysis patients, three main reasons for hypertension are volume overload, derangements of the renin–angiotensin system and sympathetic overactivity." (PMID 35888108, 2022). "In response, SCFAs, which mainly contain acetate and propionate, perform a unique role in facilitating renin secretion, eventually leading to high renin concentration and hypertension." (PMID 36457803, 2022). "Current drugs for hypertension include angiotensin-converting enzyme inhibitors, angiotensin II receptor blockers, calcium channel blockers, beta blockers, and renin inhibitors." (PMID 36278221, 2022). "We present the case of a 58-year-old male individual presenting with new-onset hypertension and severe metabolic alkalosis with spontaneous hypokalemia, in the setting of elevated aldosterone and low renin levels, suggestive of primary aldosteronism." (PMID 37908248, 2022). "Glucocorticoids trigger hypertension through numerous mechanisms, including their core mineralocorticoid action, through renin–angiotensin system activation, by augmentation of vasoactive properties, and by inhibiting the vasodilatory mechanism." (PMID 35205232, 2022). "Hyperuricemia stimulates the renin-angiotensin system and blocks the release of nitric oxide (NO) from endothelial cells, which leads to renal vasoconstriction and hypertension." (PMID 35457673, 2022). "Impaired PVAT metabolism aggravates hypertension, and this effect is dependent on the activation of local renin-angiotensin-aldosterone system (RAAS)." (PMID 36457800, 2022). "Plasma aldosterone and renin with the ratio of aldosterone to renin were measured in patients with adrenal incidentaloma with hypertension +/- hypokalemia and were positive in only one case." (PMID 36654569, 2022). "Large high flow renal arteriovenous fistula (AVF) can present with hypertension due to steal effect from renal parenchyma and subsequent activation of renin-aldosterone system." (PMID 35622189, 2022). "Dysregulation of the renin—angiotensin system (RAS), the main blood pressure regulator, is associated with several pathological conditions which include hypertension, atherosclerosis, heart and kidney diseases." (PMID 36364864, 2022). "In peripheral vascular, in absence of the vasodepressor EP receptor (EP2), PGE2 induces substantial hypertension.Many studies have indicated that PGE2 plays a role in the regulation of renal renin release." (PMID 35813612, 2022). "In the poorly controlled hypertension group, the mean age was significantly higher (P=.001) and patients had more comorbidities and higher rates of renin-angiotensin system (RAS) blocker usage compared with the other groups." (PMID 35006089, 2022). "Angiotensin II is a critical factor of the renin-angiotensin system and plays an important role in hypertension and renal failure through influences on oxidative stress, endoplasmic reticulum stress, inflammation and transcription factor activation." (PMID 35883694, 2022). "In patients with hypertension and hypokalemia, the systolic and diastolic blood pressure will be of 160 mm Hg systolic or 100 mm Hg diastolic along with high plasma renin activity observed." (PMID 35186079, 2022). "Alteration of SCFAs, and by extension dysbiosis of the gut microbiome, can stimulate hypertension through Olfr78, renin secretion, and modulation of peripheral resistance." (PMID 36499168, 2022).
Hypertension (continued). "Later, the effects of renin, aldosterone and vasopressin on top of norepinephrine contribute to explain the mechanism of hypertension." (PMID 37675017, 2022). "Blocking the angiotensin II AT1 receptor in the cerebral microvasculature can prevent cerebral ischemia and inflammation, the presence and regulation of the local renin-angiotensin system (RAS) in the cerebral microvasculature of hypertension." (PMID 35432563, 2022). "Nevertheless, endothelial dysfunction and Renin–Angiotensin System (RAS) imbalance have both been incriminated in severe outcome of COVID-19 in hypertension." (PMID 36251715, 2022). "The activation of the renin-angiotensin-aldosterone system in several tissues influences arterial hypertension by constricting the vessels." (PMID 35752756, 2022). "Risk factor modification, such as tight control of blood glucose, management of hypertension and hyperlipidemia, and the use of renin–angiotensin–aldosterone system (RAAS) blockade have been proven to help delay the progression of DKD." (PMID 35054076, 2022). "Comparison between the hypertension group and control group showed statistically significant differences in the systolic pressure and levels of 25(OH)D, renin, and triglycerides (P < 0.05)." (PMID 35814306, 2022). "The gut microbiome and its tryptophan metabolites, nitric oxide (NO), and renin–angiotensin system (RAS) are closely related to the development of hypertension." (PMID 35326133, 2022). "Inhibition of sympathetic activity and renin–angiotensin system with renal denervation (RDN) was proved to be effective in managing refractory hypertension, and improving left ventricular (LV) performance in chronic heart failure." (PMID 35571187, 2022). "Previous reports of I3C in relation to hypertension were made using a transgenic rat model with I3C as a mouse renin transgene inducer (cyp1a1ren-2 transgenic rats)." (PMID 35243102, 2022). "These ratios were adjusted for age; sex; body mass index; smoking status; presence of diabetes, hypertension, glomerulonephritis, and previous cardiovascular disease; baseline eGFR; and use of renin–angiotensin–aldosterone system blocker and statins." (PMID 36151235, 2022). "We report the case of early arterial hypertension development, marked increase of plasma renin and aldosterone, severe hypocalvaria, and low bone mineralization in a female preterm infant in-utero exposed to AT1 antagonists." (PMID 36098242, 2022). "This study identifies a relationship between rs12336898 in the SPTAN1 gene and hypertension in low-renin subjects." (PMID 35448080, 2022). "Most significantly, the low-renin SNP rs12336898 in the SPTAN1 gene, closely related to vascular wall remodeling, was associated with the development of hypertension (p-value = 1.3 × 10−6)." (PMID 35448080, 2022). "The low-renin group showed more incidence rates of new-onset hypertension (35.3%) than the high-renin group (26.5%)." (PMID 35448080, 2022). "For example, Type 2 Diabetes and hypertension are common comorbidities and they share many common mechanisms including upregulation of the renin-angiotensin-aldosterone system, oxidative stress, and inflammation." (PMID 36548597, 2022). "Among these seven individuals, two were under treatment with antihypertensive drugs (renin-angiotensin blockers) due to a history of hypertension and myocardial infarction, respectively." (PMID 35632501, 2022). "RAS activity is often increased in hypertensive patients, and low-renin hypertension has been reported to be around 20–30%." (PMID 35448080, 2022). "A study with mice harboring a missense mutation in the Cx40 gene, first observed in a human patient displaying hypertension, suggests that correct Cx40 gap junction coupling of renin-producing cells is also essential for renin secretion in the human kidney." (PMID 35511367, 2022).
Hypertension (continued). "In 17OHD, over-secretion of corticosterone, 11-deoxycorticosterone (DOC), 18-hydroxy-DOC, 18-hydroxycorticosterone, and 19-norDOC leads to low-renin hypertension and hypokalaemia." (PMID 36387847, 2022). "The disease is classically characterized by severe hypertension, hypokalemia, and metabolic alkalosis in the setting of low/suppressed aldosterone and renin levels." (PMID 35774371, 2022). "Among children with hypertension, patients with isolated systolic hypertension had lower renin concentration than patients with systolic-diastolic hypertension (26.2 [IQR: 18.6–34.2] vs. 37.8 [IQR: 27.0–49.6] [pg/mL], p = 0.014)." (PMID 35627493, 2022). "For example, there is evidence that disruptions in the renin‐angiotensin‐aldosterone system promote the development of UF and hypertension." (PMID 36117415, 2022). "CA modulates the renin-angiotensin-aldosterone endocrine axis in vitro, and in cyclosporine-induced hypertension experiments in Sprague-Dawley rats, CA significantly reduced plasma angiotensin-converting enzyme (ACE) activity." (PMID 35669732, 2022). "Since the renoprotective effects of angiotensin-converting enzyme (ACE) inhibitors before overt hypertension in AS were shown, renin–angiotensin system (RAS) inhibitor treatment should be initiated even if the patient was not hypertensive." (PMID 36292665, 2022). "Possible mechanisms explaining the development of new-onset hypertension due to SARS-CoV-2 infection include renin-angiotensin-aldosterone system (RAAS) dysregulation." (PMID 36293857, 2022). "Another report suggested that hypertension also activates the renin–angiotensin, endothelin, and WNT-β-catenin signaling pathways, subsequently inducing cartilage degeneration." (PMID 36352498, 2022). "Recurrent hypoxia, continuous stimulation of the renin-angiotensin-aldosterone system, and sympathetic nervous system activation promote hypertension development in patients with OSA." (PMID 35784707, 2022). "Apparent mineralocorticoid excess is an autosomal recessive form of monogenic disease characterized by juvenile resistant low-renin hypertension, marked hypokalemic alkalosis, low aldosterone levels, and high ratios of cortisol to cortisone metabolites." (PMID 36329487, 2022). "Possible mechanisms for the hyperuricemia and hypertension relationship include activation of the intra-renal renin-angiotensin system, urate deposition in the lumen of the nephrons and inflammation." (PMID 36962833, 2022). "By RAAS activation, renin can lead to arterial hypertension, progressing nephropathy, cardiovascular remodelling and, therefore, accelerate cardiovascular events." (PMID 34751898, 2022). "In 1 single occasion, the Lewis genetic resistance to hypertension appearedovercome by introducing over-expressed mouse Renin genes in a mRen2.Lewcongenic strain." (PMID 39076226, 2022). "The cut-off value of active renin concentration to predict hypertension was 17.2, and to predict systolic-diastolic hypertension it was 33.9 [pg/mL], respectively (respectively)." (PMID 35627493, 2022). "The multifaceted receptor, SUCNR1, has been attributed to kidney physiopathology via stimulation of the local and systemic renin–angiotensin system, development of metabolic syndrome, and hypertension." (PMID 36551549, 2022). "Cardiac remodeling is a common complication of hypertension, in which renin-angiotensin system plays a central role." (PMID 36204568, 2022). "In brief, BAC targets ACE/ACE2 to enhance endothelium-dependent vasorelaxation and reduce vascular inflammation to attenuate hypertension as a potential modulator of the renin–angiotensin system." (PMID 35359841, 2022). "Current treatment strategies to limit cardiovascular damage during hypertension are aimed at lowering arterial pressure, especially by inhibition of the renin-angiotensin system by angiotensin-converting enzyme inhibitors or angiotensin type 1 antagonists." (PMID 35133978, 2022).
Hypertension (continued). "Current guidelines for the management of arterial hypertension suggests the use of combination therapies based on renin-angiotensin-aldosterone system inhibitors, diuretics and dihydropyridine calcium-channel blockers for most of hypertensive patients." (PMID 35966525, 2022). "RAS inhibitors such as renin inhibitors, angiotensin-converting enzyme inhibitors (ACEIs), and Angiotensin receptor blockers (ARBs) are therapeutically indicated to treat hypertension." (PMID 35625041, 2022). "An initial study suggests that hypotension caused by anemia or treatment with an angiotensin II receptor blocker increases the number of interstitial renin-expressing cells, whereas hypertension decreases their number compared to control animals." (PMID 35511367, 2022). "Several pathophysiological mechanisms impair insulin signaling in hypertension, such as renin–angiotensin, sympathetic nervous systems, and oxidative stress." (PMID 35455055, 2022). "The renin-angiotensin-aldosterone system (RAAS) is the best known biologic pathway; DNA methylation on related genes is strongly associated with hypertension incidence." (PMID 35655232, 2022). "A state-of-the-art translational mouse model of hypertension-accelerated DKD has recently been established, induced by adeno-associated virus (AAV)-mediated renin overexpression in the uninephrectomized (UNx) diabetic db/db (db/db UNx-ReninAAV) mouse." (PMID 35884965, 2022). "Obesity leads to an increase in intra-abdominal pressure, and the infiltration of fat into the kidney, which further leads to glomerular hypertension and activation of the renin–angiotensin–aldosterone system, thus promoting the occurrence of hypertension." (PMID 36359836, 2022). "Heart failure is characterized by activation of the renin-angiotensin-aldosterone system, which is involved in the regulation of cardiac hypertrophy and hypertension." (PMID 35126818, 2022). "Beyond the JG apparatus, the CD has been proposed as a major second site of (pro)renin synthesis in the kidney, particularly under conditions of excess local Ang II such as diabetes and hypertension." (PMID 35710133, 2022). "The renin-angiotensin-aldosterone system (RAAS) is a major target for treating hypertension and preventing various complications." (PMID 37908267, 2022). "The influence of renin–angiotensin–aldosterone system (RAAS) inhibitors on the critically ill COVID-19 patients with pre-existing hypertension remains uncertain." (PMID 35321649, 2022). "miR-663 has been reported to target renin (REN) and apolipoprotein E (APOE) mRNAs and a decrease in miR-663 has been associated with an increase in renin mRNA in patients with hypertension." (PMID 36712680, 2022). "It is unlikely, therefore, that the hypertension in corin kcKO mice was due to an overall enhanced activity of the renin–angiotensin–aldosterone system." (PMID 36232551, 2022). "NAFLD can induce systemic effects such as inflammation, activation of the renin-angiotensin system, activation of the sympathetic system and insulin resistance, which are pathophysiological mechanisms for the development of hypertension." (PMID 36155120, 2022). "Of note, international recommendations allow direct measurement of active renin concentration and plasma renin activity to diagnose primary aldosteronism and monogenic forms of hypertension." (PMID 35627493, 2022). "Increased sodium levels lead to hypertension by increased reabsorption and electrolyte retention, retaining sodium passed through renal tubules and stimulating the renin–angiotensin–aldosterone system in the brain." (PMID 36362997, 2022). "Lyon hypertensive rats were developed in France in the 1970s from a Sprague-Dawley strain and are considered a model of low-renin hypertension, similar to DSS and 11-deoxycorticosterone acetate (DOCA)-salt rats." (PMID 36231118, 2022). "An important mediator of hypertension and heart failure (HF) is angiotensin II (Ang II), the main effector of the renin-angiotensin system (RAS)." (PMID 36311201, 2022).